LINC01836 (long independently transcribed non-coding RNA 1836)
Gene: Long non-coding RNA gene on chromosome 19 (782,119 to 787,548, forward strand). Ensembl gene ENSG00000267530.
Diseases named in the same sentence as LINC01836 in open-access papers:
LINC01836 is named in the same sentence as 5 diseases in open-access papers, as found by Europe PMC text mining. Sharing a sentence is not in itself a finding about the gene and the disease. The quoted sentences say what the papers report.
head and neck cancer (1 paper, 2024). A primary or metastatic malignant neoplasm affecting the head and neck. "Although LINC01836 is upregulated in colon and rectal cancers, it was down-regulated in kidney, lung, and head and neck cancers." (PMID 39695079, 2024).
lymph node metastasis (1 paper, 2022). "High expression of Linc01836 was associated with histological stage (p = 0.002) and lymph node metastasis (p = 0.006)." (PMID 35370745, 2022).
tumor (2 papers, 2022 to 2024). "Additionally, high expression of LINC01836 was associated with good OS but not with advanced tumor stages in other organs." (PMID 39695079, 2024). "It was worthy to mention that the T stage represented the depth of tumor invasion; even though no statistical significance was found in the T stage and TNM stage in general, it displayed obvious correlation between increased serum Linc01836 expression and lymph node metastasis." (PMID 35370745, 2022).
LINC01836 also shares sentences with these, for which no sentence is quoted: colorectal cancer (1 paper); rectal cancer (1).